CD46 (CD46 molecule)
Diseases named in the same sentence as CD46 in open-access papers (continued):
Sharing a sentence is not in itself a finding about the gene and the disease.
infection (continued). "While these variants readily infected CD46-edited MDBK cells, they had reduced infection in primary cells from the CD46-edited heifer compared to unedited controls." (PMID 40431646, 2025). "TraT can also engage with the host CD46 through a specific domain of the complement control protein, which enhances the infection of cells." (PMID 39809778, 2025). "Fibroblasts from CD46 edited cloned calves showed dramatically reduced BVDV susceptibility, measured by flow cytometry at 20 h post-infection (hpi), compared to those directly from Banner or his unedited clones." (PMID 40573367, 2025). "We also noted a slightly reduced infection by HAdV-B11 in these cells, despite a minor increase in CD46 expression." (PMID 40980888, 2025). "Given the reduced infection of HAdV-D types in A549-ΔCD46 cells, we next wanted to characterize their binding affinity and mode of interaction with CD46." (PMID 40980888, 2025). "Similar results were seen in monocytes; all virus strains replicated in the unedited cells while only minimal infection of the adapted viruses was detected in monocytes from the CD46-edited heifer." (PMID 40431646, 2025). "Further infection experiments with PhoPeV using CD46 knockout and complemented cell lines will be useful to conclude the analysis of the role of CD46 in cell entry of PhoPeV." (PMID 39861896, 2025). "Most viruses showed markedly reduced infection in A549-ΔCD46 cells, indicating a strong preference for CD46." (PMID 40980888, 2025). "Nevertheless, given the high level of HS expression in MDBK cells, rapid HS adaptation likely minimized the selection pressure for BVDV to use the gene-edited CD46 A82LPTFS receptor to initiate infection." (PMID 40431646, 2025). "First, (i) expression of the MeV receptor CD46 and (ii) its correlation with primary infection rates were analyzed." (PMID 38339240, 2024). "Similar observations were made in the A549 CD46‐KO cell line at 3 days post infection although the phenotype after infection with GoraVir was lost upon higher MOI." (PMID 38037840, 2024). "In fact, infection of the MIA PaCA‐2 CD46‐KO cells with GoraVir was similar to uninfected cells, suggesting the virus was no longer able to enter the cells." (PMID 38037840, 2024). "In particular, the cell lines with the highest CD46 density and consequently the highest primary infection rates also showed the most intense bands." (PMID 38339240, 2024). "The highest intensity was observed in HROC57 and BON1 cells, which also had higher CD46 expression as well as higher primary infection rates compared to the other examined cell lines." (PMID 38339240, 2024). "CD46 can control early infection of the pathogen by autophagy, as shown that the CD46-Cyt-1/GOPC pathway participated in directing S. pyogenes to autophagic degradation." (PMID 36761775, 2023). "The aim of this work is to determine which of the two receptors, DSG2 and CD46, is involved in the attachment of the virus to the host, and what role they play in the early stages of infection." (PMID 37921471, 2023). "It has been described that upon binding to CD46, HHV-6A, causes a rapid downregulation of this receptor that is slower upon infection by HHV-6B." (PMID 36032156, 2022). "B16-CD46 cells stably expressed CD46 in vitro and enabled efficient mLOAd703 infection as seen by the induced expression of CD40L and 4-1BBL." (PMID 35141399, 2022). "TraT also interacted with host CD46 in a specific complement control protein domain-dependent manner, whereby facilitating the cellular infection and tissue dissemination of E. tarda." (PMID 35768577, 2022). "Although DSG-2 expression is lower than CD46 in all lines, the Ad3 knob can utilize both DSG2 and CD46 for infection, leading to similar transduction as HDAd5/35 capsid vectors." (PMID 35681750, 2022). "As a promoter of cellular infection, it interacts with the host cell receptor CD46 in a specific CCP domain-dependent manner, whereby facilitating cellular and tissue invasion." (PMID 35768577, 2022).
infection (continued). "The B16 cells are modified to express human CD46 to facilitate infection of adenoviruses with a serotype 35 fiber such as LOAd703 virus." (PMID 35141399, 2022). "When using luciferase as a reporter for infection, we were able to detect CD46-dependent infection with Stealth-K1 but the luciferase levels were significantly lower than those obtained when cells were infected with Stealth-A09." (PMID 33534834, 2021). "HAdV-B35 saw significant decreases in transduction in all three cell lines, whereas blocking CD46 had a minimal effect on HAdV-C5 infection." (PMID 34452348, 2021). "While CD46 serves as a receptor for apical infection of BAEC by BVDV, the receptor for basolateral infection remains to be elucidated." (PMID 33300445, 2021). "It is well established that treatment of MDBK cells with monoclonal antibodies against CD46 can block infection." (PMID 34204224, 2021). "This modification retargets the viruses to infect CD46+ cells, thereby enabling infection of most cells, including B cells." (PMID 33666760, 2021). "(in vivo and in vitro) MV infection model using human CD46 transgenic mice and cells isolated from transgenic mice." (PMID 34408631, 2021). "(in vivo and in vitro) MV infection model in transgenic mice expressing human CD46 in the CNS (NSE-CD46) and primary neurons." (PMID 34408631, 2021). "Our results indicate that CD46 is an apical protein and that this property is maintained after infection by BVDV." (PMID 33300445, 2021). "Membrane cofactor protein CD46 is a complement regulatory protein that has been identified as a receptor for BVDV in the initiation of infection." (PMID 33300445, 2021). "The differential levels of CD55 and CD46 in VSV-infected cells prompted us to investigate the pattern of incorporation of these proteins into the virus envelope as a function of time post infection." (PMID 33652918, 2021). "The levels of CD46 in the infected cell lysates between 19 and 24 h post infection (hpi) were below the minimum level of detection (second panel from top F and G)." (PMID 33652918, 2021). "In particular the two peptide domains E66QIV69 and G82QVLAL87 of the complement control protein module 1 (CCP1) are crucial for the binding of BVDV—preincubation of MDBK cells with an anti-CD46 serum leads to a strong reduction in infection efficiency." (PMID 32781607, 2020). "Many cancer types like prostate tumors have a strong expression level of measles receptor CD46, which facilitates effective infection of tumor cells by this oncolytic virus." (PMID 32336951, 2020). "CD46 protein expression was reported to be low in normal tissues, which would limit the infection of normal cells during therapy and thereby reduce side effects." (PMID 32957644, 2020). "The gonococcus interacts with CD46-cyt1 via the Type IV pilus (Tfp), recruiting CD46-cyt1 at the site of infection." (PMID 32582714, 2020). "A study showed that higher expression of CD46 on myeloma tumors compared to healthy tissues mediates tropism of the virus for malignant plasma cells and higher sensitivity of cancer cells to infection and destruction by MV-NIS." (PMID 32336951, 2020). "The CD46-Cyt-1-GOPC-VPS34-BECN1 complex pathway is also operating in autophagy induction during infection of human cells by GAS and Neisseria gonorrhoeae that both bind to CD46." (PMID 32274388, 2020). "The downregulation of CD46-cyt1 and the remodeling of the lysosome later during infection promotes intracellular survival." (PMID 33014885, 2020). "Ngo recruitment of CD46-cyt1 to the site of infection is mediated by Tfp retraction; ΔpilT, a retraction-deficient mutant, fails to recruit CD46-cyt1." (PMID 30753248, 2019). "Our CMV high-throughput inhibition assay in epithelial cells screened a panel of mAbs and identified two clones that limit infection by targeting CD46, but fail to block viral entry of fibroblasts." (PMID 31221976, 2019).
infection (continued). "Collectively, cell-type specific CD46-protein containing complexes would likely be important during unique steps of virus entry in cells that require endocytosis for infection." (PMID 31221976, 2019). "CD46-cyt1 downregulation occurs slowly, but by 9 hours post-infection (hpi), total cellular levels of CD46-cyt1 are significantly reduced in infected cells." (PMID 30753248, 2019). "Soluble Nrp2 protein demonstrated clear reduction of infection for both cell types in comparison to soluble CD46 protein, a result consistent with previous findings." (PMID 31221976, 2019). "A high-throughput inhibition assay is employed to screen these antibodies for their ability to limit infection, and mAbs targeting CD46 are identified." (PMID 31221976, 2019). "Throughout infection, Ngo mounts a counter-attack on the autophagic pathway by downregulating CD46-cyt1 and disturbing lysosome homeostasis." (PMID 30753248, 2019). "Throughout infection, the pathogen slowly downregulates CD46-cyt1 and remodeling of lysosomes, another key autophagy component, and these activities ultimately promote intracellular survival." (PMID 30753248, 2019). "ARPE-19 cells, treated with all three anti-CD46 mAbs, were evaluated for infection with strains TB40/E wt and AD169BADrUL131." (PMID 31221976, 2019). "Taken together, these results indicate that the autophagic response to Ngo infection is initiated by CD46-cyt1/GOPC." (PMID 30753248, 2019). "The increase in LC3-II levels in response to infection was significantly lower in Cyt1-treated cells compared to Ctrl-treated cells, suggesting that CD46-cyt1 engagement is necessary for autophagy induction." (PMID 30753248, 2019). "This is potentially due to the facts that the vector uses CD46 for infection, a receptor that is expressed at higher levels on primitive HSCs than on more differentiated bone marrow cells and that it can transduce non-dividing HSCs." (PMID 29766024, 2018). "The presence of CD46 on the cell surface gave only a small increase in luciferase expression in the short term, most likely indicating that infection following direct intra-tumoural injection of virus can be less receptor-dependent." (PMID 29898782, 2018). "Other than HCMV, HHV-7 was also demonstrated to up-regulate the expression of CD59 and CD46 on the infected cells during the late stage of infection." (PMID 28670306, 2017). "If IFNγ contributed to protection of NSPCs in the CD46+ model, then we would predict greater apoptosis in CD46+/IFNγ-KO mice during infection." (PMID 27178303, 2016). "The drastic difference in efficacy with which the Ad35 and Ad43 fiber knobs inhibited Ad43 infection that we observed is likely due to the differing affinities these knobs have for CD46." (PMID 27462785, 2016). "Newly committed neuronal cells were lost at all time points post-infection in CD46+/IFNγ-KO pups and at 7 and 10 dpi in CD46+ pups." (PMID 27178303, 2016). "Infections in all the different CD46 transgenic mouse lines were limited, since the animals were resistant to wtMeV isolates, and they required suppression of innate immunity to yield viable infections." (PMID 27657109, 2016). "CD46+ and CD46+/IFNγ-KO pups were mock or MV-infected on postnatal day 2 (P2) and whole brains were harvested at 3, 7, or 10 days post-infection (dpi)." (PMID 27178303, 2016). "In particular, IFNγ is required for long-term control of neurotropic viruses in CD46+ adult mice and other infection models." (PMID 27178303, 2016). "Dependence of Ad43 infection on CD46 was further demonstrated in a similar experiment in which soluble CD46 protein (sCD46) was tested as infection inhibitor." (PMID 27462785, 2016). "Prior to infection, the cells were incubated with the recombinant Ad35 fiber knob domain—a strong competitive blocker of CD46." (PMID 27462785, 2016). "Flow cytometric analysis revealed that NSPCs were reduced in CD46+/IFNγ-KO mice at 3, 7, and 10 days post-infection (dpi), but were unaffected in CD46+ mice." (PMID 27178303, 2016).
infection (continued). "We demonstrate a significant, CD46-dependent increase in EOC cell transduction with Ad5T*F35++ infection in EOC cells in comparison to the parental Ad5 control vector." (PMID 27229159, 2016). "Studies suggest this phosphorylation is essential for Neisseria attachment and cytoskeletal rearrangement and that Neisseria also stimulates proteolytic cleavage of CD46 tails during infection." (PMID 26054645, 2015). "The results obtained for CD46- and SLAM-dependent cell-associated virus production 2 days after infection suggest that PEA motif substitutions, with one exception, only have a slight negative effect on Moraten virus assembly." (PMID 26587021, 2015). "CD46 serves as receptor for several pathogens and dogma states that pathogens binding CD46 abuse the receptor’s ability to promote IL-10 switching, thus furthering an infection-promoting environment." (PMID 26084023, 2015). "On epithelial cells, infection leads to the shedding of CD46 at the same time as the bacteria induce apoptosis and cell death." (PMID 26054645, 2015). "There are reports which show that pathogen receptor CD46 on the cell surface can trigger cell autophagy to control infection by Streptococcus." (PMID 25070150, 2014). "Despite such widespread distribution, CD46 expression levels on normal cells are generally low and fall under the threshold of receptor density required to initiate and sustain an MV-Edm infection." (PMID 24646176, 2014). "The C-type lectin DC-specific intercellular adhesion molecule 3-grabbing nonintegrin DC-SIGN has been shown to be an attachment receptor to enhance CD46/CD150-mediated infection of Dendritic cells." (PMID 25171206, 2014). "The membrane protein CD46, a ubiquitous cell surface pathogen receptor, can bind Streptococcus to trigger cell autophagy, which is a critical step in the control of infection." (PMID 25070150, 2014). "Consistent with their resistance to infection, normal bronchial epithelial cells barely expressed CD46 (MFI = 21)." (PMID 23586034, 2013). "Immediately upon infection, attenuated measles virus induces a first transient wave of autophagy, via a pathway involving its cellular receptor CD46 and the scaffold protein GOPC." (PMID 24086130, 2013). "We have previously reported that HeLa cell infection with the attenuated Edmonston (Ed)-MeV strain induces autophagy as soon as 1.5 hours post infection via the engagement of the CD46-Cyt-1/GOPC pathway." (PMID 24086130, 2013). "Although a variety of other receptors including H protein dependent or independent ones can be used for MV-Edm infection, it has been reported that their efficiency is far lower than CD46." (PMID 23009685, 2012). "Infections with IC323-EGFP wtMV were unaffected by the presence of monoclonal antibodies directed against CD46 and CD150, that were previously shown to neutralize MV infections." (PMID 21901103, 2011). "In our recent screen of species D Ads for infection of B cell cancers, we observed that most were largely independent of sialic acid for infection, but instead used a combination of CD46 and αv integrins for infection and killing." (PMID 21453281, 2011). "Upon infection, CD46 is phosphorylated at tyrosine 354, clusters beneath microcolonies of N. gonorrhoeae and induces a transient release of Ca2+ from intracellular stores." (PMID 21949708, 2011). "CD46 and integrins on the cell surface are important for binding, uptake, and infection by species B adenoviruses." (PMID 21455297, 2011). "In the case of Edmonston-EGFP MV, we chose to use owl monkey kidney (OMK) cells, which are known to be deleted for the critical SCR1 domain of CD46, and are normally resistant to infection by vaccine strains of MV." (PMID 21901103, 2011). "Signs of the infection, such as neck stiffness, tremble and listless, were observed in 20% of infected CD46+/+ mice, which had decreased survival compared to control groups, 80% versus 100%." (PMID 21124975, 2010).
infection (continued). "Recognition of pathogens by CD46 is thought to trigger autophagy, which serves as a critical step to control infection." (PMID 20941397, 2010). "Since a down-regulated CD46 expression would have reduced the binding capacity of all 3 anti-CD46 mAbs to the same extent, these findings strongly suggest that CD46 is masked during infection with Ad11 and Ad35." (PMID 20041185, 2009). "Using flow cytometry analysis, we assessed CAR and CD46 intensity in A549 cultures following infection with Ad5-CRAD or Ad5F35-CRAD vector at low MOI." (PMID 20041185, 2009). "For Ad35 we identified a novel CD46-independent infection mechanism, which is dependent on sulfated HSPGs (Ad35 receptor function of HSPGs)." (PMID 18974862, 2008). "Nontransgenic mice infected with N. meningitidis cleared the bacteria within 24 h, while infection of CD46 transgenic mice resulted in three different disease patterns." (PMID 17311106, 2007). "To study meningococcal sepsis we set up an intravenous (i.v.)infection model in CD46 transgenic mice." (PMID 17311106, 2007). "CD46 also affects various cellular activities in response to pathogen or complement binding, and thus influences the host response to infection." (PMID 16984646, 2006). "The homozygous CD46 gene edit reduced in vitro BVDV susceptibility to a level comparable to that observed in cells with a complete CD46 gene deletion (CD46Δ), demonstrating that the CD46 A82LPTFS substitution eliminates the virus’ ability to use CD46 to initiate infection." (PMID 40431646, 2025). "Interestingly, though all the SS lines had similar expression of the CD46 MV entry receptor, there was a clear difference in viability and replication, following infection with MV-s-NAP, between Fuji and the other 3 lines." (PMID 41235176, 2025). "Therefore, primary skin fibroblast cell lines were established from four cloned calves (two each CD46-edited and unedited) for ex vivo infection studies." (PMID 40573367, 2025). "Notably, 17 out of the 18 HAdV-D types tested required CD46 for efficient infection of A549 cells, with HAdV-D32 being the only exception, and with HAdV-D39 depending weakly on CD46." (PMID 40980888, 2025). "Similarly, monocytes from the CD46-edited heifer were resistant to infection by both the unadapted PI-86-2021 and the in vivo HS-adapted PI-86-2022 serum samples." (PMID 40431646, 2025). "Indeed, serving as an HHV-6A receptor to enter cells, CD46 is downregulated following infection with HHV-6A." (PMID 39906411, 2025). "Infection of HerPs/-virus -6A may be another virulent contributor to the development of AMD by downregulating complement receptor CD46 in RPE and choroid endothelial cells." (PMID 36738354, 2023). "However, when the experiment was repeated using the Roesrath variant, which was subjected to 30 passages in culture, blockade of CD46 had less effect on infection." (PMID 38041163, 2023). "In our study, heterologous expression of mCD46 in human cells facilitated the cellular infection of TX01, while antibody blocking of the natural mCD46 on mouse cells impaired TX01 invasion, suggesting that the interaction between TraT and CD46 is vital to TX01 infection." (PMID 35768577, 2022). "The broad infection range may relate to the receptor used by this virus as many HAdV-B types can use the CD46 protein as their entry receptor." (PMID 34861769, 2022). "We investigated whether the weak interaction between HAdV-D10K and CD46 was sufficient to result in cell attachment and infection." (PMID 35399606, 2022). "Thus, the complement regulatory factor CD46 acts as a pathogen sensor able to initiate autophagy upon infection." (PMID 37425656, 2022). "Interestingly, trans-complementation with CD46-CTS comprising a short cytoplasmic tail did not only restore WT-susceptibility, but even enhanced infection with BVDV-1, BVDV-2 and HoBiPeV." (PMID 34839792, 2022).